CD4 (CD4 molecule)
Diseases named in the same sentence as CD4 in open-access papers (continued):
Sharing a sentence is not in itself a finding about the gene and the disease.
tumor (continued). "In high-risk patients, we found elevated levels of gene signatures for CD8+ T cells, CD4+ T cells, dendritic cells, and macrophages, suggesting augmented immune cell infiltration in the tumor, a characteristic of a more inflammatory tumor microenvironment and potential immunosuppression." (PMID 40427760, 2025). "Tumor-associated, but not bone marrow derived, Ly6Chigh monocytes significantly inhibited CD4+ T cell proliferation in vitro." (PMID 41397968, 2025). "Microglia are essential for anti-GBM CD4+ T-cell responses and the inhibition of tumor growth." (PMID 40302809, 2025). "Notably, the number of CD206+ M2 TAMs was significantly reduced, whereas the number of tumor‐infiltrating CD4+ and CD8+ T cells was markedly increased in syngeneic tumor tissues generated by co‐injection of BMDMsPRDX1‐KO cells." (PMID 41306557, 2025). "At the same time, it exhibited a positive correlation with cells that may promote tumor progression, such as activated CD4 + T cells, dendritic cells, NK T cells, central memory CD4 + T cells, effector memeory CD4 + T cells and Th2 cells." (PMID 40577282, 2025). "Other approaches for inducing tumor-cognate CD4+ T cells have been explored." (PMID 39704984, 2025). "The P1 monotherapy vaccine increased the proportion of cDC1 and cDC2 subsets in the lymph nodes, which presented antigens to CD8+ T cells and CD4+ T cells, respectively, promoting the activation and differentiation of T cells in the dLN and generating a potent anti-tumor immune response." (PMID 40733687, 2025). "When melanoma-bearing mice were exposed to such modified MWCNTs under 808 nm NIR laser radiation at a dose of 1 W/cm2 for 5 min, suppression of tumour growth and an improved number of lymph-draining CD4+ and CD8+ T cells were observed in the spleen, with increased antitumour efficacy." (PMID 40710305, 2025). "Overall, we delineated cell–cell interaction landscape of tumor cells and immune cells and revealed that Plac1+ tumor cells recruited CD4+ T cells through the CXCL11/CXCR3 axis and then induced Treg differentiation through PVR/TIGIT to shape the immunosuppressive TME of HNSCC." (PMID 40056047, 2025). "Some TILs behave as effector cells, such as CD8+ and natural killer lymphocytes, inducing a cytotoxic cascade resulting in tumor cell death, while other TILs show a regulatory role inhibiting the anti‐tumor activity of effector T cells, mainly CD4+ lymphocytes." (PMID 40789673, 2025). "The upregulation of MHCII on tumor cells facilitated tumor control by CD4+ T cells." (PMID 39885128, 2025). "CD8_Exhausted and CD4_Exhausted T cells are significantly enriched in tumor tissues." (PMID 40452847, 2025). "Interestingly, ENO1 is also related to B cells, CD4+ T cells, and macrophages in the infiltrating tumor tissues (P < 0.001)." (PMID 41049005, 2025). "Shared tumor antigens activate specific CD4+/CD8+ T cells and trigger antitumor immune responses." (PMID 41200280, 2025). "After confirming tumor growth inhibition in the absence of evident toxicity, spleens were collected from treated and control mice, and splenocytes were re-stimulated ex vivo with CD4 and CD8 epitope peptides derived from universal tumor associated antigens (Telomerase and Survivin)." (PMID 39706891, 2025). "Future studies should incorporate immunohistochemical analyses of tumor-infiltrating immune cells (e.g., CD4+ and CD8+ T cells, IL-6R expression, macrophage markers) to delineate the relationship between systemic cytokine alterations and intratumoral immune activity." (PMID 41303495, 2025). "Using NicheNet analysis, we predicted target genes in CD4+ T cells that could be influenced by the interactions from microglia, myeloid and tumor cells, and found that memory signature was highly enriched among these target genes in M002-treated CD4+ T cells." (PMID 39885128, 2025).
tumor (continued). "The system effectively expands tumor-infiltrating lymphocytes, resulting in a 6.62-fold increase in CD4+ T cells compared to controls, along with elevated populations of CD8+ T cells and Granzyme B+ cytotoxic cells, as well as enhanced pro-inflammatory cytokine expression." (PMID 41267084, 2025). "Additionally, neoantigen load was also associated with higher content of CD8 T cells, macrophages, and CD4 memory T cells in multiple tumor types." (PMID 40519905, 2025). "Moreover, the expression of IGLL5 was correlated with three types of tumor-infiltrating immune cells (TICs): naive B cells, plasma cells, and activated CD4 memory T cells." (PMID 40566633, 2025). "A well-established approach to stimulating CD4+ T helper responses in cancer vaccines involves using xenogeneic or non-tumor-specific peptides, such as the synthetic helper peptide PADRE (derived from keyhole limpet hemocyanin [KLH]) and tetanus toxoid-derived helper peptides." (PMID 40543509, 2025). "Notably, high NAP1L5 expression correlated with increased infiltration of resting CD4+ memory T cells, implicating its potential influence on the tumor immune microenvironment." (PMID 40786510, 2025). "Sustained STAT3 activation leads to the proliferation of many tumor cells.The widespread expression of IL-21R in immune enables IL-21 to activate macrophage, DCs, NK cells, B cells, NK T cells, CD4+T cells, CD8+ T cells, Treg cells, Th17 cells, follicular helper T cells, etc.." (PMID 40469178, 2025). "Of note, the suppressive effect of CD4+ T cells was significant when survival, but not when tumor progression, was measured, conceivably because monitoring of tumor progression was halted when 2 or more mice reached maximum tumor size in the untreated group." (PMID 40162209, 2025). "We find that the natural CD4+ T cell response to a growing tumor is phenotypically and functionally diverse, with distinct subsets including type 1 helper (Th1), T follicular helper (Tfh)-like, and regulatory T cell (Treg) lineages appearing as early as 9 days after tumor implantation." (PMID 40196575, 2025). "Immune regulation: In ESCC, FABP9 may affect anti-tumor immune responses by regulating CD4 + T cell infiltration." (PMID 40717587, 2025). "Furthermore, BRCA growth is inhibited in vivo by CD4 T cells alone, and T cell-dependent tumor regression is induced via indirect pro-inflammatory/immune impact." (PMID 40985028, 2025). "Additionally, a significant presence of TNF superfamily ligand-receptor interactions was observed in CD4+ TGF-β1+ T cells with other tumor-infiltrating T cells in ICB-NRs." (PMID 40054456, 2025). "Additionally, CQ treatment reduces Th2+ CD4+ T cells, which support tumor eradication, while positively shaping the TME." (PMID 40611330, 2025). "We then assessed the direct effect of transferred CD4+ T cells on GBM tumor cells in vivo." (PMID 39885128, 2025). "The combination of InVivoMab and RT significantly increased tumor infiltration of CD4+ (12.05 ± 7.35%) and CD8+ (31.09 ± 3.82%) cells compared with the control groups (0.72 ± 0.21%, 9.68 ± 5.04%, respectively), indicating enhanced recruitment and activation of effector T cells." (PMID 41614850, 2025). "In particular, while cytotoxic CD4+ T cells have long been observed in tumor models and patients with cancer, recent work has highlighted their functional importance in recognizing MHC class II–restricted tumor antigens, and their regulation in vivo in patients." (PMID 40299576, 2025). "Additionally, recent evidence highlights the clinical benefits of neoantigen vaccines, particularly those that elicit tumor-reactive CD4+ T cell responses." (PMID 40543509, 2025). "illustrated that antiviral CD4+ T cells enhance the responses of tumor-specific CD8+ T cells." (PMID 40698086, 2025). "CD4+ T cells contribute by directly killing tumor cells or modulating the tumor microenvironment." (PMID 41404065, 2025).
tumor (continued). "Furthermore, cytotoxic CD4+ T cell subsets can directly eliminate tumor cells, either in a major histocompatibility complex (MHC) class II-dependent or -independent manner." (PMID 40543509, 2025). "The induction of B7-H3+LAG3+ CD4+ T cells from the bone marrow of pediatric B-ALL patients and their correlation with high cytotoxic granule expression suggests a pivotal role of CD4+ T cells in controlling tumor growth in B-ALL, characterized by high HLA class II expression." (PMID 40070836, 2025). "CD4 + T cells play a crucial role in tumor immunity and therapy." (PMID 39992487, 2025). "Therefore, circNHSL1 knockdown inhibits glutamine uptake by gastric cancer cells in TME, inhibits tumor growth in vivo, and reduces glutamine competition with CD4+ T cells." (PMID 40296917, 2025). "Within the TME, CD4+ T cells demonstrate marked functional plasticity through differentiation into Th1, Th2, or Treg subsets, exerting either inhibitory or promotive effects on tumor progression." (PMID 41320679, 2025). "Beyond their immunosuppressive function, CD4+ T cells may also modulate the activity and recruitment of other immune cells, contributing to the broader immunoregulatory network within the tumor." (PMID 40948762, 2025). "In addition, CD8+ TRegs were elevated in stromal lymph aggregates, while CD4+ TRegs were also elevated at NOS2+ tumor edges when compared with tumor satellite and/or core regions." (PMID 40663402, 2025). "To further investigate whether dynamic changes in CD4+ T cell density within the TME provide early insights into immunotherapy efficacy, we subjected additional PyMT tumor-bearing ICI-treated hCD4-KI mice to in vivo 64Cu-CD4-Nb1-PET imaging." (PMID 40561008, 2025). "Here, 33% of mice (7 of 21 animals) showed an increased 64Cu-CD4-Nb1 uptake in the tumor core." (PMID 40561008, 2025). "Importantly, B cells can present cognate tumor-derived antigens to CD4+ T helper cells and cytotoxic CD8+ T cells." (PMID 41030446, 2025). "Furthermore, immunofluorescence staining confirmed high CD70 expression in MC3Ri tumor cells and its colocalization with CD4.Treg and CD8.Tex cells, particularly in perivascular regions." (PMID 40876452, 2025). "Therapies discovered here would enrich CD4 T helper cell activity to promote anti-tumor immune recognition and thus may work either as a single agent or synergistically with CD8 T cell-directed immunotherapies." (PMID 41210994, 2025). "In contrast, T cells were present in tumor subsets, 26% for CD4 (50/193) and 40% for CD8 (75/189)." (PMID 38968186, 2024). "In addition, the anti-tumor effects of DNMTi -zebularine depend on the co-existence of CD4+ and CD8+ T lymphocytes and the presence of CD4+ T cells is necessary for CTLs to kill tumor cells." (PMID 38755254, 2024). "Notably, high TIMELESS expression was associated with increased infiltration of activated CD4+ T cells and immunosuppressive Th2 cells and decreased infiltration of CD8+ T cells, cytotoxic Th1 cells, and dendritic cells in LUAD tumor tissues." (PMID 38261568, 2024). "As expected, monotherapy of RocA significantly increased CD4+/PD-1+ T cells in LLC tumor tissues." (PMID 38833034, 2024). "By investigating the levels of CD8+ T and CD4+ T cells infiltration in tumor tissue through flow cytometry and immunofluorescence staining, it was found that monotherapy by inulin or Oxa could exert certain immune activation effects." (PMID 38721274, 2024). "Furthermore, the combination of PD-1 and VEGFR-2 blockade increased PD-1 expression in tumor-infiltrating CD4+ T cells, and those cells were able to promote vasculature normalization in hepatocellular carcinoma models." (PMID 39596815, 2024). "Ferroptosis can alter the tumor microenvironment, for example, by secreting inflammatory factors to activate immune-related cells, such as CD4+ T cells and CD8+ T cells, or by producing metabolic molecules such as phospholipid peroxides, thereby influencing immune cells." (PMID 38786003, 2024).
tumor (continued). "Similarly, tumours treated with PI3K/mTORi or PI3K/mTORi+PD‐1i exhibited higher proportions proliferating Ki67+ T cells (% of total CD4+ or CD8+ T cells)." (PMID 38711203, 2024). "We found that the proportion of cluster 3 in blood was negatively associated with CD4+ T cell infiltration in tumor (OR = 0.71, 95%CI = 0.51-0.99, p < 0.05; not significant after FDR correction)." (PMID 38653982, 2024). "It was investigated whether anti-CD47 Ab regulated intra-tumor vasculature and functioned through increased CD4+ cell infiltration." (PMID 38398223, 2024). "CD4 + T cells can target tumor cells in various ways, either directly by eliminating tumor cells through cytolytic mechanisms or indirectly by modulating the tumor microenvironment." (PMID 39105866, 2024). "CD4+ T cells also can enhance tumor control by modulating macrophage function." (PMID 38519525, 2024). "In other words, GPR65 was mainly expressed on CD8 + T cells, CD4 + T cells, and tumor associated macrophages, but not on 8-cluster cells (osteoblasts or OS cells)." (PMID 38218960, 2024). "In the tumor environment and in the circulation of patients, CD4+ cytotoxic T lymphocytes (CTLs) express cytolytic effector molecules, including granzymes, perforin, and other granule-associated proteins such as natural killer cell granule Protein 7 (NKG7) and granulysin." (PMID 39507526, 2024). "Additionally, HCS cells loaded with DOX can induce an immune response by activating CD3+ and CD4+ T cells, inhibiting tumor growth." (PMID 38751816, 2024). "Moreover, apCAFs have been reported to present antigens to CD4+ T cells, implicating their involvement in the anti-tumor process." (PMID 38540204, 2024). "Moreover, treatment with CAR-T cells only led to more CD4+ cells being retained outside the tumor than treatment with combination therapy." (PMID 39445067, 2024). "Taken together, these findings suggest that oHSV-1 treatment induced tumor rejection by eliciting an effective antitumoral immune response characterized by a significative recruitment of both CD4 + and CD8 + T cells, capable of protecting mice from subsequent tumor challenges." (PMID 39334370, 2024). "Moreover, ALDOA levels in tumor tissues negatively correlate with the number of infiltrating immune cells, including macrophages, CD4+ T cells, and CD8+ T cells." (PMID 39201614, 2024). "Similarly, dysfunctional cDCs, termed “mregDC,” possess a unique immunoregulatory program upon uptake of tumor antigens and seem to preferentially engage with exhausted, antigen-experienced CD4 T cells." (PMID 38903502, 2024). "CD4+ TILs infiltration was closely correlated with tumor depth (p = 0.020)." (PMID 39264227, 2024). "Next, we investigated the anti-tumor efficacy of CD4+ and CD8+ T cells with Hes1-cKO." (PMID 39702544, 2024). "This may suggest a strong positive relationship between HDAC7 and tumor infiltrating cells (TILs), especially considering CD4+ T cell populations whose levels generally correlate positively with HDAC7 expression and negatively with HDAC2 expression." (PMID 39063083, 2024). "Moreover, several studies have shown that the adoptive transfer of CD4+ T cells can induce tumor regression in mouse models." (PMID 38412034, 2024). "Within the immune cells, CD4 + factors can secrete cellular tissue to enhance immune response and kill tumor cells, while CD8 + factors can secrete inhibitory cells to suppress CD4 + factors, inhibit B cell synthesis, and thereby inhibit immune response, resulting in decreased immune function." (PMID 38605359, 2024). "Importantly, using immunohistochemistry analysis based on our tissue microarray, we found that CHMP2B was highly expressed in tumor tissue, and CD4 and CD8 were more likely to be positive in the CHMP2B-negative group." (PMID 38169571, 2024). "These CD4+ T cell subpopulations could promote the anti-tumor immune response by recruiting and activating B and T cells." (PMID 39093451, 2024).
tumor (continued). "For example, CD4+ T cell depletion retarded tumor growth by increasing effector T cell function." (PMID 38650951, 2024). "Of note, exhausted T cells (CD8_Tex, CD8_Tprf, and CD4_Th cells), which could be reactivated by ICIs, persisted in tumor samples and were more enriched in ATC samples." (PMID 38478516, 2024). "Additionally, in the ambiance of HPV+ tumor cells, CD4+T cells exhibit enhanced IFNγ secretion, which is critical to orchestrating adaptive immune response against viral and tumoral antigens." (PMID 39105803, 2024). "Due to the paucity of tumor-specific helper neoantigens identified in pre-clinical cancer models, it is currently unclear which type of CD4+ T cell antigen most improves anti-tumor vaccine efficacy: tumor-specific neoantigens or tumor-unrelated universal helper antigens." (PMID 39040850, 2024). "Furthermore, castalagin, which is enriched in bacteria associated with effective immunotherapeutic responses (e.g., family Ruminococcaceae and genus Alistipes), improves the ratio of CD8+ cells to FOXP3+CD4+ cells in the tumor microenvironment." (PMID 38803568, 2024). "By analysing the immune response of a patient who showed exceptional response to the H3K27M peptide vaccine, the authors found CD4+ T cells as crucial drivers of this response, and pointed to mechanisms through which the T cells recognise and fight tumour cells." (PMID 38880657, 2024). "These insights suggest that 9,10-DiHOME may act as a mediator, increasing Treg levels within the tumor microenvironment, thereby modulating CD4 on TD CD4+ effects on HCC." (PMID 39336774, 2024). "CD8+ T cell population in the tumor of 5LO-deficient mice did not change, but CD4+ T cells including CD4+ FoxP3+ T cells were significantly decreased." (PMID 38786066, 2024). "In addition, at the boundary between tumour and normal tissue, some stromal cells or myeloid cells recruited by CD4+T cells can bypass MHC-I molecules and present tumour antigens to CD4+T cells via MHC-II molecules." (PMID 39816386, 2024). "Moreover, Kim’s investigation into the prognostic implications of tumor-infiltrating FoxP3- CD4+ T cells in biliary tract cancer illustrates the critical role of these T cells in CCA." (PMID 39335203, 2024). "However, mixing HDVax-induced, Treg cell-depleted mItgb1-specific CD4+ T cells with LDVax-induced effector cells abrogated T3 tumour rejection." (PMID 39048822, 2024). "Notably, NFAT-1 is involved in tumor cell survival, invasive migration, and tumor-induced CD4+ T-cell anergy by releasing pro-inflammatory cytokines, including PlGF." (PMID 39457506, 2024). "Among CD4+ T cells, a Th1-phenotype is considered desirable for anti-tumor immunity." (PMID 38653982, 2024). "CD4+ T lymphocytes were stimulated by the A549 tumor cell lineage in all experimental groups." (PMID 39599846, 2024). "The presence of a large number of activated phenotypes of plasmacytoid DCs suggests that CD4 effector T cells may promote anti-tumor immunity by enhancing the ability of DCs to induce CD8 T cell responses and directly promoting the expansion of CD8 T cells." (PMID 39575712, 2024). "By reducing the dose and number of administrations of TGFβ and Cox2 siRNA (3 doses), we could demonstrate the reduction in the tumor was concomitant with an increase in infiltration of CD4+ and CD8+ T-cells into the tumor." (PMID 38204925, 2024). "Indeed, shTFEB tumors had a more variegated TIME compared to wild type tumors, but PT treatment turned the TIME of shTFEB tumors toward immunosuppression, by decreasing anti-tumor populations as CD4+T-helper lymphocytes, Vγ9Vδ2 T-lymphocytes and NK cells." (PMID 39107857, 2024). "Additionally, treatment of colon cancer using oncolytic herpes simplex virus (oHSV) (O-HSV1211) modified to express both IL-12 and CXCL11 leads to increased infiltration of CD8+ T and CD4+ T cells into the tumor site." (PMID 39055561, 2024).